CTSL (cathepsin L)
Diseases named in the same sentence as CTSL in open-access papers (continued):
Sharing a sentence is not in itself a finding about the gene and the disease.
lung carcinoma (continued). "In the present study, we examined the expression of SARS-CoV-2 entry genes, including ACE2, TMPRSS2, CTSL, and AXL in primary human airway epithelial cells isolated from 11 lung cancer patients." (PMID 36148455, 2022). "We further compared the expression levels of CTSL, TMPRSS2, and FURIN in normal lungs and lung cancers." (PMID 35414771, 2022). "Decreased expression of CTSL in lung cancer cells has been reported to inhibit EMT mediated by TGF-β, and CTSL increases after the treatment of cells with TGF-β." (PMID 31370861, 2019). "We further compared the expression of CTSL and ACE2 mRNA in normal lungs and lung cancers and found that CTSL expression was 66.4-fold higher in normal lungs and 54.8-fold higher in lung cancer tissues, as compared to ACE2 mRNA levels in the respective tissues." (PMID 35414771, 2022). "In fact, we also found that CTSL inhibition could suppress EMT-mediated invasion and metastasis of lung cancer cells." (PMID 30732622, 2019). "Thus, the lowest level of cathepsin L activity was observed for the reovirus-resistant lung carcinoma cell culture, A549, as well as non-tumors NKE and hTERT-BJ, both intracellularly and in supernatants." (PMID 39772250, 2024). "Thus, we compared the expression of CTSL and ACE2 mRNA in normal lungs and lung cancers." (PMID 35414771, 2022). "In this study, we examined expression levels of ACE2, TMPRSS2, and cathepsin L in human airway epithelial cells derived from never smokers, former smokers, current smokers, patients with COPD, or lung cancer." (PMID 33425965, 2020).
melanoma (18 papers, 2007 to 2024). A malignant, usually aggressive tumor composed of atypical, neoplastic melanocytes. "While cathepsin B is predominantly expressed in melanoma cells, cathepsin L is mainly found in cancer-associated fibroblasts surrounding the invading melanoma cells." (PMID 38474423, 2024). "Membrane association of cathepsin L in human and murine melanoma cells suggests extra-lysosomal functions of cathepsin L in metastasis." (PMID 17488522, 2007). "In the cancer cell lines, the top three cell lines with a high CTSL mRNA expression were giant cell tumor, melanoma, and chondrosarcoma, respectively." (PMID 35155389, 2022). "Cathepsin L1 overexpression has been proven to lead to the degradation of fibronectin, resulting in the onset of melanomas." (PMID 34827106, 2021). "For example, subpopulations of high metastatic potential of murine B16 melanoma cell lines were found to express higher levels of CTSL when compared to their low-metastatic counterparts." (PMID 25384089, 2014). "This is consistent with the observation that blocking the secretion of CTSL can abolish metastasis of melanoma cells, a process which requires ECM degradation." (PMID 21687683, 2011). "This study shows that cathepsin L facilitates high metastatic B16 melanoma cell invasion and migration." (PMID 17488522, 2007). "In this study we have examined the effect of cathepsin L down-regulation on the in vitro behavior of highly metastatic B16F10 melanoma cells." (PMID 17488522, 2007). "To determine if the level of cathepsin L protein correlated with relative cathepsin L message levels determined by RT-PCR, we performed a Western blot analysis of several B16 melanoma clones." (PMID 17488522, 2007). "In this work we have examined the in vitro contribution of cathepsin L to the behavior of high-metastatic B16 F10 melanoma cells." (PMID 17488522, 2007). "Nevertheless, an intracellular role for cathepsin B in matrix degradation has been identified, and also, three forms of extracellularly active cathepsin B and two forms of active cathepsin L have been described in the highly invasive melanoma cell line MV3." (PMID 17620116, 2007). "We take these results to mean cathepsin L has direct effects on the cell motility and contributes its proteolytic action to the active invasion of melanoma cells." (PMID 17488522, 2007). "We have shown cystatin C, a potent cathepsin L inhibitor, blocks motility and invasion of melanoma cells." (PMID 17488522, 2007). "Our results show cathepsin L makes a major contribution to melanoma cell invasion, particularly through cell migratory influences." (PMID 17488522, 2007). "To circumvent problems with inhibitors, we have produced anti-sense clones to cathepsin L in B16 melanoma cells." (PMID 17488522, 2007). "Intracellular expression of an antibody to cathepsin L has also been shown to block cathepsin L secretion and dramatically inhibit melanoma metastasis." (PMID 17488522, 2007). "The involvement of cathepsin L in tumor progression is less evident than for cathepsin B but its contribution to the invasive and metastatic potential of malignant cells such as oncogenically transformed fibroblasts and melanoma cells has been demonstrated." (PMID 26157794, 2015). "Likewise, in melanoma, hypoxia–induced upregulation of cathepsin L was shown to be regulated post-transcriptionally by an IRES sequence." (PMID 24086473, 2013). "We have examined the role of cathepsin L in highly metastatic B16F10 murine melanoma cells through genetic antisense constructs of cathepsin L. The effects of cathepsin L antisense were examined for melanoma cell proliferation, invasion, migration and adhesion." (PMID 17488522, 2007). "Based on earlier work in the literature, we hypothesized cathepsin L would make a major contribution to B16 melanoma invasion." (PMID 17488522, 2007). "The intriguing possibility that cathepsin L might be inducing cell migratory factors in melanoma needs to be tested with gene array analysis." (PMID 17488522, 2007).
melanoma (continued). "Cathepsin L contributed to melanoma cell invasion and also augmented melanoma cell migration." (PMID 17488522, 2007). "Furthermore, staining intensity increases in cells closer to the invasive front in the intradermal part of the lesion, indicating that the activation of fibroblasts and concomitant cathepsin L expression are important facilitators of malignant melanoma dissemination." (PMID 38474423, 2024). "Cathepsin L down-regulation also does not appear to be linked to expression of the cysteine protease inhibitor cystatin C. Cathepsin L does however make a significant contribution to B16F10 melanoma cell invasion, particularly through cell migration." (PMID 17488522, 2007). "C3 had previously been described as a substrate of CTSL expressed by human melanoma cells but in those studies, C3 was not processed into C3a and C3b but rather fully degraded." (PMID 24315997, 2013). "More recently, non-metastatic melanoma cells were converted to metastatic cells by over-expression of cathepsin L." (PMID 17488522, 2007). "Although cathepsin L has been shown to contribute to melanoma cell invasion, other properties of melanoma cells such as migration, adhesion and proliferation have not been well studied." (PMID 17488522, 2007). "Indeed, a previous study showed that acidic pH promotes experimental pulmonary metastasis of human melanoma cells in athymic nude mice by up-regulating the expression of the proteolytic enzymes MMP-2, MMP-9, cathepsin B, and cathepsin L and the proangiogenic factors VEGF-A and IL-8." (PMID 30836626, 2019). "Similarly, suppression of cathepsin L activity impairs invasion of glioma cells but not melanoma cell lines." (PMID 25927437, 2015). "In our study, comparisons of band intensities of legumain and cathepsin L did not statistically correlate, but the melanoma cell lines derived from patient biopsies seemed to express a stronger 25 kD mature cathepsin L immunoband in the cell lines with a strong 36 kD active legumain band." (PMID 20074384, 2010). "Interestingly, those melanoma cell lines from patients showing a strong expression of the 36 kD active legumain form, seemed to have a stronger expression of the 25 kD active cathepsin L form compared to the 30 kD form, although not statistically significant." (PMID 20074384, 2010). "Finally, the inhibition of melanoma cell migration via down-regulation of cathepsin L appears to be independent of cystatin C expression." (PMID 17488522, 2007). "In addition, CTSL also may switch the melanoma cell phenotype from non-metastatic to highly metastatic and increased tumor invasion and migration." (PMID 27351223, 2016). "We have observed expression of cystatin E/M, legumain, cathepsin B and L in multiple melanoma cell lines, and an inverse correlation between secreted levels of the cysteine protease inhibitor and cellular activities of legumain and cathepsin B (but not cathepsin L) was detected." (PMID 20074384, 2010).
ovarian carcinoma (18 papers, 2014 to 2026). A malignant neoplasm originating from the surface ovarian epithelium. "The top three cancer types with mutated CTSB were prostate, esophagogastric, and ovarian cancers, while those with mutated CTSL were adrenocortical carcinoma, and esophagogastric and endometrial cancers." (PMID 35155389, 2022). "This review examines the diverse roles of CTSL in ovarian cancer progression, focusing on how its expression, localisation, and extracellular release are altered within the hypoxic and acidic conditions typical of the tumour microenvironment." (PMID 42122181, 2026). "Overall, the evidence highlights CTSL as a central regulator of invasion, angiogenesis, and relapse in ovarian cancer, underscoring its potential as a target for new therapies in aggressive disease." (PMID 42122181, 2026). "Expression of cathepsins B and D is elevated in ovarian cancer and expression of a different cathepsin family member, cathepsin L, increases the invasion and metastatic capacity of ovarian cancer cells." (PMID 37899138, 2023). "Retention of red signal was also obtained when the CTSL-overexpressed cells were treated with QC in the presence of Z-FY(tBU)-DMK, which confirmed the role of CTSL in mediating QC-induced MOMP in ovarian cancer cells." (PMID 33919392, 2021). "In this study, we investigated the role of pseudogenes in ovarian cancer, with a particular focus on CTSL pseudogene 8, as qRT-PCR confirmed its upregulation in metastatic ovarian cancer tissues." (PMID 33933142, 2021). "Here, we demonstrated that QC cytotoxicity in ovarian cancer was mediated by CTSL, and QC induced autophagic and apoptotic cell death by promoting LMP and MOMP." (PMID 33919392, 2021). "Although the pro- and anti-oncogenic functions of CTSL appear to be context-dependent, our work suggested that CTSL plays a role in promoting ovarian cancer cell death upon QC treatment." (PMID 33919392, 2021). "We reported earlier that the antimalarial drug Quinacrine (QC) also has anticancer activity and here we discovered that QC significantly upregulates cathepsin L (CTSL) and promoting autophagic flux in ovarian cancer." (PMID 33919392, 2021). "In this study, we screened RNA expression patterns in metastatic ovarian cancer tissues via RNA sequencing and identified non-coding CTSL pseudogene 8 (lnc-CTSLP8), which was significantly upregulated." (PMID 33933142, 2021). "As a result of this phenomenon, CTSL knock-down in ovarian cancer cells SCOV3 resulted in increased apoptosis induced by paclitaxel (the most common drug in the management of ovarian cancer)." (PMID 31340550, 2019). "Effects of CTSL knockdown on ovarian cancer cell proliferation, apoptosis, migration, and invasion were also studied." (PMID 27351223, 2016). "In summary, these findings suggest that CTSL functions as a carcinogenic factor in human ovarian cancer tissues." (PMID 27351223, 2016). "We found that the mRNA levels of CTSL were significantly higher in ovarian cancer tissues in comparison with adjacent normal tissues (P < 0.01)." (PMID 27351223, 2016). "The results showed that CTSL expression in ovarian cancer specimens was significantly upregulated compare with that in the adjacent non-tumoral tissue." (PMID 27351223, 2016). "To extend our clinical studies and investigate its biological function, we examined the effect of CTSL on the progression of ovarian cancer in SKOV3 and SKOV3/TAX cell model." (PMID 27351223, 2016). "To determine the expression levels of CTSL in tumor tissues from human ovarian cancer patients, we assessed 58 pairs of ovarian cancer specimens and adjacent normal tissues by qRT-PCR." (PMID 27351223, 2016). "Moreover, the CTSL-overexpressed OV2008 cells showed the opposite effect on treatment with QC for 24 h, which confirmed that QC-mediated CTSL induction promotes apoptotic cell death in ovarian cancer cells." (PMID 33919392, 2021).
ovarian carcinoma (continued). "In contrast, we demonstrated that high CTSL levels sensitized ovarian cancer cells to QC treatment." (PMID 33919392, 2021). "On the other hand, CtsL secreted by ovarian cancer cells mediated the tumor progression." (PMID 31340550, 2019). "Knocking-down of CTSL in ovarian cancer cells could decrease cell proliferation, migration, and invasion, and potentiate apoptosis induced by paclitaxel, suggesting CTSL may contribute to Paclitaxel resistance in ovarian cancer." (PMID 27351223, 2016). "Our study revealed that inhibition of CTSL could enhance the chemosensitivity of ovarian cancer cells." (PMID 27351223, 2016). "We next studied the impact of CTSL silencing on ovarian cancer cell proliferation." (PMID 27351223, 2016). "We then examined the CTSL expression in clinical ovarian cancer specimens by IHC staining." (PMID 27351223, 2016). "In our study, ovarian cancer cells resistant to paclitaxel showed upregulation of CTSL." (PMID 27351223, 2016). "CTSL knockdown can enhance sensitivity of ovarian cancer cells to paclitaxel." (PMID 27351223, 2016). "We next studied the impact of CTSL silencing on ovarian cancer cell migration and invasion." (PMID 27351223, 2016). "The results of this study may clarify the role of CTSL in ovarian cancer and elucidate CTSL is a potential target for the treatment of patients with ovarian cancer." (PMID 27351223, 2016). "In the current study, we firstly investigated the expression level of CTSL in the large sample size of 58 cases of ovarian cancer, and results showed that the expression level of CTSL mRNA was significantly increased in ovarian cancer tissues compared with normal paired tissues." (PMID 27351223, 2016). "Overexpression of CTSL was found in ovarian cancer tissues and cell lines." (PMID 27351223, 2016). "In this study, we investigated the expression and function of CTSL in ovarian cancer." (PMID 27351223, 2016). "CTSL has been found to be overexpressed in ovarian cancer, however, the role of CTSL in chemoresistance is currently unknown." (PMID 27351223, 2016). "Furthermore, CTSX is upregulated in metastatic gastric cancer, enhanced levels of CTSB and CTSL accompany malignant ovarian tumors, and CTSS directly supports invasion of hepatocellular carcinoma cell lines." (PMID 27802179, 2016). "Therefore, differences in CTSL levels could offer a therapeutic window allowing QC to preferentially target ovarian cancer cells—especially those that have developed chemoresistance—while maintaining minimal overall toxicity in vivo." (PMID 33919392, 2021). "Thus, CTSL may be a novel biological marker and potential therapeutic target for the treatment of ovarian cancer." (PMID 27351223, 2016). "We also determined whether CTSL could regulate chemoresistance in ovarian cancer cells." (PMID 27351223, 2016). "Furthermore, CTSL silencing significantly potentiated apoptosis induced by paclitaxel in SKOV3/TAX compared with control shRNA, suggesting CTSL contributes to paclitaxel resistance in ovarian cancer cells and that CTSL silencing can enhance paclitaxel-mediated cell apoptosis." (PMID 27351223, 2016). "Taken together, the data suggest that QC-induced autophagy and CTSL upregulation promote a positive feedback loop leading to excessive autophagic flux, LMP, and MOMP to promote QC-induced cell death in ovarian cancer cells." (PMID 33919392, 2021). "We uncovered that QC-induced CTSL upregulation promotes autophagic flux, LMP, and MOMP, resulting in autophagic and caspase-dependent cell death in ovarian cancer." (PMID 33919392, 2021). "Genetic (shRNA) and pharmacological (Z-FY(tBU)-DMK) inhibition of CTSL markedly reduces QC-induced autophagy, LMP, MOMP, apoptosis, and cell death; whereas induced overexpression of CTSL in ovarian cancer cell lines has an opposite effect." (PMID 33919392, 2021).
ovarian carcinoma (continued). "To further investigate the effect of CTSL in the proliferation ability of ovarian cancer cells, we established stable SKOV3 and SKOV3/TAX cell line with down-regulation of CTSL by shRNA sequences against CTSL (SKOV3/TAX-CTSL-shRNA)." (PMID 27351223, 2016). "IHC staining showed overexpression of CTSL was observed in 70.69% (41/58) of ovarian cancer specimens when compared with adjacent non-neoplastic tissues (32.76%, 19/58), the difference of CTSL expression was statistically significant." (PMID 27351223, 2016). "The results of MTT assay showed that knockdown of CTSL in SKOV3 and SKOV3/TAX cells decreased cell proliferation, suggesting that CTSL might be involved in the development of ovarian cancer." (PMID 27351223, 2016). "The IHC and real-time PCR results showed that the difference of CTSL expression between ovarian cancer and the adjacent non-tumourous ovarian tissues was statistically significant." (PMID 27351223, 2016). "Importantly, OC cells have elevated CTSL levels compared to non-neoplastic tissues, and this elevated CTSL expression has been shown to promote ovarian cancer cell proliferation and invasion and resistance to chemotherapy, with secreted CTSL playing a role in cancer progression." (PMID 33919392, 2021). "High expression of CTSL was observed in 70.69% (41/58) of ovarian cancer specimens when compared with adjacent non-neoplastic tissues (32.76%, 19/58), the difference of CTSL expression was statistically significant (P < 0.001), suggesting that CTSL may play an oncogenic role in ovarian cancer." (PMID 27351223, 2016). "In addition, we noticed that the expression of CTSL was significantly increased in the paclitaxel-resistant cell line (SKOV3/TAX cells) compared with SKOV3 cells, suggesting that CTSL may play an oncogenic role in ovarian cancer." (PMID 27351223, 2016). "We found that knockdown of CTSL expression by shRNA significantly reduced the proliferation rate of SKOV3 and SKOV3/TAX cells compared with the control vector, indicating that depletion of endogenous CTSL could attenuate the proliferation of ovarian cancer cells in vitro." (PMID 27351223, 2016). "In this study, we discovered that QC significantly upregulates cathepsin L (CTSL) but not CTSB and CTSD, implicating the specific role of CTSL in promoting QC-induced autophagic flux in ovarian cancer." (PMID 33919392, 2021).